CTLA4 (cytotoxic T-lymphocyte associated protein 4)
Diseases named in the same sentence as CTLA4 in open-access papers (continued):
Sharing a sentence is not in itself a finding about the gene and the disease.
cancer (continued). "Immune checkpoint inhibitors, such as those targeting CTLA‐4 and PD‐1, have demonstrated significant clinical responses in other cancers, and our study identifies high expression of Treg markers like FOXP3 and CTLA‐4 in HB, suggesting these may serve as important immunotherapeutic targets." (PMID 40099956, 2025). "Immune checkpoint inhibitors, such as PD-1 inhibitors (nivolumab, pembrolizumab, cemiplimab), CTLA-4 inhibitor (ipilimumab), and PD-L1 inhibitors (atezolizumab, durvalumab, avelumab), have transformed cancer treatment by helping the immune system recognize and attack cancer cells." (PMID 40352591, 2025). "However, both the “CTLA-4 signaling in Cytotoxic T-lymphocytes” and the “PD-1, PD-L1 cancer immunotherapy” pathways appear paradoxically inactivated during csACR; the negative z-scores indicate downstream messaging and effector proteins are not inhibited as would be expected." (PMID 41337937, 2025). "ICIs act by targeting key immune regulatory pathways, such as cytotoxic T-lymphocyte-associated protein 4 (CTLA-4), programmed cell death protein 1 (PD-1), and programmed death ligand 1 (PD-L1), thereby enhancing the immune system’s ability to detect and eliminate cancer cells." (PMID 40697379, 2025). "Immune checkpoint therapy (ICT) targeting cytotoxic T lymphocyte antigen 4 (CTLA-4) and programmed cell death protein 1 (PD-1) has provided remarkable clinical responses over the past decade, but these benefits are restricted to a subset of patients with cancer." (PMID 40460830, 2025). "Additionally, the regulation of response to biotic stimulus may illustrate cellular adaptations to biotic stress, relevant to immune reactions against cancer presence and therapeutic agents like anti-CTLA-4 antibodies." (PMID 40721801, 2025). "The pathogenesis of cutaneous immune-related adverse events (irAEs) observed in patients with cancer treated with immune checkpoint inhibitors remains variable, with one critical determinant being whether patients are treated with PD-1, PD-L1, and CTLA-4 antibodies." (PMID 39879305, 2025). "Immune checkpoint inhibitors (ICIs), namely, anti-cytotoxic T lymphocyte-associated protein 4 (CTLA-4) monoclonal antibody Ipilimumab and anti- and programmed cell death 1 (PD-1) monoclonal antibodies Nivolumab, and Pembrolizumab, have improved the treatment outcomes for many other cancer types." (PMID 40230698, 2025). "Additionally, research has found that risk scores constructed based on cuproptosis-related genes correlate with immune checkpoint molecules, such as PD-L1, CTLA4, targeted therapy-related genes, cancer stem cell characteristics, and sensitivity to chemotherapy and targeted drugs." (PMID 40070821, 2025). "Interestingly, the neurological manifestations observed in the proband, especially demyelination, recapitulate some of the side effects of cancer immunotherapy using immune checkpoint inhibitors (ICIs), such as the CTLA4-blocking monoclonal antibodies ipilimumab and tremelimumab." (PMID 40149457, 2025). "Furthermore, altered signaling pathways and genetic polymorphism in checkpoint genes such as CTLA-4, PDCD (which encodes PD-1) and PDL-1 may play a role in variable responses to ICIs in cancer patients." (PMID 40109334, 2025). "Furthermore, as PD-1/PD-L1 and CTLA4 inhibitors have been extensively evaluated clinically in patients with many cancer types, combinations of FoxP3 regulators and ICIs may be possible to test where ICIs do not work optimally." (PMID 40034859, 2025). "Immunotherapy for cancer has entered a new phase since the discovery of therapeutics that can block certain immunological checkpoints, such as the cytotoxic T lymphocyte antigen-4 (CTLA-4) and, more recently, the programmed death-1 receptor (PD1) and its ligand (PDL1)." (PMID 38258094, 2024).
cancer (continued). "These universal gene expression programs may account for the widespread application of immunotherapy (e.g., PD-1/PD-L1 inhibitors and CTLA4 inhibitors) in a variety of cancers, in contrast to the targeted therapy which has limited indications in specific cancer types." (PMID 38744958, 2024). "In contrast to drug-targeted therapy, immunotherapy uses the body’s own immune system to attack cancer cells and includes immune checkpoint inhibitors such as programmed cell death 1 (PDCD1; also known as PD-1) and cytotoxic T-lymphocyte associated protein 4 (CTLA4) inhibitors." (PMID 39070147, 2024). "These proteins, including programmed cell death-1 (PD-1), cytotoxic T-lymphocyte antigen-4 (CTLA-4), and T-cell immunoglobulin and mucin domain 3 (TIM3), represent the immune regulatory function of co-inhibitory receptors associated with T-cell dysfunction and exhaustion in many cancers." (PMID 38723011, 2024). "Moreover, various immune phenotypes of senescent T cells have been associated with malignant tumors, such as the downregulation of CD27 and CD28, and the upregulation of CD57, cytotoxic T-lymphocyte-associated protein 4 (CTLA-4) and killer cell lectin-like receptor subfamily G (KLRG-1)." (PMID 39200181, 2024). "More specifically, CTLA-4 inhibitors enhance T-cell activation and promote an immune response against cancer cells by blocking the downregulation of immune responses, while PD-1/PD-L1 inhibitors allow T-cells to effectively attack cancer cells by blocking inhibitory interactions." (PMID 38539511, 2024). "The strategy of blocking inhibitory immune checkpoints such as cytotoxic T lymphocyte-associated protein 4 (CTLA-4), programmed cell death protein 1 (PD-1), programmed death ligand 1 (PD-L1), and lymphocyte activation gene 3 (LAG-3) has revolutionized the landscape of cancer treatment." (PMID 38632994, 2024). "High responses to monoclonal antibodies targeting the immune checkpoints cytotoxic T-lymphocyte-associated protein 4 (CTLA-4) (e.g., ipilimumab) and programmed death 1 (PD-1) (e.g., pembrolizumab and nivolumab) led to the approval of these checkpoint inhibitors for the treatment of various cancers." (PMID 38835346, 2024). "Furthermore, in recent years, cancer patients undergoing treatment with anti-CTLA-4 and other immune checkpoint inhibitors (CPI) that block inhibitory molecules and enhance immune activation against tumours, have been found to develop autoimmune and immune-mediated inflammatory diseases." (PMID 39496592, 2024). "The immune regulatory proteins, cytotoxic T lymphocyte antigen (CTLA-4), programmed cell death protein (PD-1) and its ligand, PD-L1, are important immune system regulators known as immune checkpoint receptors and are pivotal in the pathogenesis of cancer development." (PMID 39727645, 2024). "However, the efficacy of anti-CTLA-4 is relatively limited in some cancer types." (PMID 38756774, 2024). "Interestingly, SPAG5 overexpression was correlated with high levels of lymphocyte CD8+, macrophages, neutrophils, dendritic and B cells, positively associated with PD-1/PDL1, LAG3, GZMB and CTLA4 and SPAG5 antigens were suggested as valid immune stimulatory targets for anti-cancers therapy." (PMID 39164278, 2024). "Despite the promising outcomes of anti-CTLA4 and anti-PD-1 antibodies in treating cancer, including solid tumors and hematopoietic malignancies, many of the treated patients do not respond well to the ICB, and those who initially do may not have durable clinical benefits." (PMID 39618825, 2024). "METTL1 may be effective in the treatment of HNSC and other cancers through the targeting of other immune checkpoints, including the T-cell Ig and ITIM structural domains (TIGIT), or the cytotoxic T lymphocyte-associated protein 4 (CTLA-4)." (PMID 39289775, 2024). "However, the impact of anti-CTLA-4 is limited in some cancer types." (PMID 39409171, 2024).
cancer (continued). "It achieves this by facilitating cancer cell survival, migration, metastasis, chemoresistance, and evasion of immune responses, particularly in response to immunosuppressive agents like programmed cell death protein 1 (PD1) and cytotoxic T-lymphocyte-associated antigen 4 (CTLA4)." (PMID 38535990, 2024). "However, limited response rates of cancer patients to PD-1 and CTLA-4 blockade have been reported." (PMID 38785930, 2024). "For instance, CPI therapy against programmed cell death protein 1 (PD1), or cytotoxic T-lymphocyte associated protein 4 (CTLA4) targets predominantly T cells, while inhibition of the CD47-signal-regulatory protein α (SIRPα) axis focuses on the interactions between cancer cells and macrophages." (PMID 38475820, 2024). "Hence, Cancer cells establish immune privilege by upregulating the expression of inhibitory ligands, such as PD-L1, CTLA-4, LAG-3, TIM-3, and GAL9, which engage their cognate receptors on T cells, effectively transmitting a “stop” signal that abrogates T cell activation and function." (PMID 39450177, 2024). "This is the first single-center, real-world study describing the occurrence of endocrine and non-endocrine irAEs following use of CTLA4, PD-1 and PD-L1 inhibitors in a broad range of solid tumor malignancies and to investigate their association with cancer survival." (PMID 38681767, 2024). "Consequently, to produce durable anticancer responses, immunotherapy based on PD-1/PD-L1 inhibition is used in conjunction with other available therapeutic options, including CTLA-4 blockade, cancer vaccines, target-based small molecule inhibitors (SMIs) and agonist antibodies." (PMID 38660299, 2024). "Indeed, the use of antibiotics before anti-PD-1/PD-L1 or anti-CTLA4 antibody monotherapy was associated with negative clinical outcomes in several meta-analyses and prospective studies, regardless of cancer type and geographic region." (PMID 38668936, 2024). "Additionally, combining this therapy with other modalitiesholds promise, such as the standard GBM treatment of temozolomide,immune checkpoint inhibitors (e.g., anti-PD-1 or anti-CTLA-4 antibodies), and cancer vaccines, to potentiallyenhance the immune response." (PMID 39556101, 2024). "In pathway analysis and cancer immune correlation analysis, we observed that SRSFs were associated with the activation or inhibition of multiple immune pathways, and were also closely related to the expression of multiple immune checkpoints (LAG3, CD274, CTLA4, TIGIT, PDCD1)." (PMID 38015716, 2023). "We also applied the Srps on large‐scale dataset with anti‐PD‐1/PD‐L1/CTLA4 treatment and found that Srps performed certain accuracy to predict treatment response on eight of total 25 cohorts (AUC > 0.7), which demonstrated the potential utility of Srps in pan‐cancer immunotherapy response." (PMID 38107057, 2023). "Cancer immunotherapy (CIT) has gained increasing attention and made promising progress in recent years, especially immune checkpoint inhibitors such as antibodies blocking programmed cell death 1/programmed cell death ligand 1 (PD-1/PD-L1) and cytotoxic T lymphocyte-associated protein 4 (CTLA-4)." (PMID 36463323, 2023). "Immune checkpoint blockade in T cells using antibodies that target cytotoxic T-lymphocyte-associated protein 4 (CTLA-4), programmed cell death protein 1 (PD-1) or its ligand PD-L1, and more recently lymphocyte-activation gene 3 (LAG3) has proven therapeutic efficacy in different cancer types." (PMID 37781391, 2023). "Cytotoxic T-lymphocyte-associated protein 4 (CTLA4), Ras association domain-containing protein 1 isoform A (RASSF1A), and signal transducer and activator of transcription 4 (STAT4) genes regulate the cell cycle, apoptosis, and the autoimmune response against cancer." (PMID 37893134, 2023).
cancer (continued). "Currently, cancer immunotherapy has progressed rapidly and has become an important scientific breakthrough of cancer treatment, especially the application of ICIs like anti-programmed cell death protein 1/anti-programmed cell death 1 ligand 1 (anti-PD-1/PD-L1) and anti-CTLA-4." (PMID 37416062, 2023). "The impact of Ipilimumab (Cytotoxic T-Lymphocyte Antigen 4 (CTLA-4)-antagonist), Nivolumab and Pembrolizumab (Programmed cell Death protein 1(PD-1)-antagonists), and Atezolizumab (Programmed Death-Ligand 1(PD-L1)-antagonist) on overall survival in cancer patients is relevant." (PMID 37240983, 2023). "Thus, immunologically targeting CSCs while simultaneously blocking PD-1/PD-L1 and/or CTLA-4-mediated immune suppression may significantly enhance the outcome of current cancer immunotherapies." (PMID 37251931, 2023). "Similarly to CTLA-4, PD-1 is an inhibitory membrane receptor protein of cytotoxic T lymphocytes that binds to the PD-L1 and PD-L2 expressed by many cells, such as DCs and cancer cells." (PMID 37239166, 2023). "Therefore, the current cancer immunotherapy targeting a single target, such as PD-1/PD-L1 inhibitor, Cytotoxic T-lymphocyte Antigen-4 (CTLA-4) inhibitor, and Chimeric antigen receptor (CAR) T-cell therapy (CAR-T), has very limited therapeutic effect on most cancers." (PMID 37006233, 2023). "It was proposed that the blockage mechanism of CTLA-4 could be used in cancer treatments." (PMID 37110545, 2023). "Finally, since injection of anti–CTLA-4 antibodies can also promote IL-21 production, our findings may be relevant to autoimmune adverse events in cancer patients receiving checkpoint immunotherapy, where autoantibodies frequently emerge." (PMID 37466652, 2023). "Blocking immunological checkpoints such as cytotoxic T lymphocyte-associated protein 4 (CTLA-4), programmed cell death ligand 1 (PD-L1), and programmed cell death protein-1 (PD-1), has made a great contribution to the immunotherapy of various cancers in recent years." (PMID 37251370, 2023). "To date, immune-checkpoint blockade (ICB) therapies targeting cytotoxic T lymphocyte-associated antigen 4 (CTLA4/CD152), programmed cell death protein 1 (PD-1/CD279), and programmed death-ligand 1 (PD-L1) have presented unprecedented responses in significant percentages of cancer patients." (PMID 36826125, 2023). "CTLA-4 blocking (anti-CTLA-4) ICIs, such as ipilimumab and tremelimumab, PD-1 blocking (anti-PD-1) ICIs, such as nivolumab and pembrolizumab, and PD-L1 blocking (anti-PD-L1) ICIs, such as atezolizumab, durvalumab, and avelumab, help T cells stay active and attack cancer cells." (PMID 38202123, 2023). "In addition, in some cases, clinical efficacy might fall short of expectations due to the complex regulatory mechanisms of PD-1/PD-L1 or CTLA-4 in cancer immunity." (PMID 37355637, 2023). "For example, the addition of VC may enhance the efficacy of combined anti-CTLA-4 and anti-PD-1 blockade against tumors, while in vitro studies have found that high doses of VC may target mitochondria, which in turn leads to cancer stem cell death." (PMID 36787291, 2023). "Thus, blocking CTLA-4 by monoclonal antibodies could increase the effector functions of T-cells to kill cancer cells." (PMID 37415164, 2023). "Furthermore, CTLA-4 has been proven to act as an efficient therapeutic target in cancer treatment." (PMID 36765782, 2023). "Furthermore, its soluble form has also been detected in the serum of patients with cancer and autoimmune disorders, suggesting that CTLA-4 may be involved in functions beyond the immune system regulation." (PMID 36901916, 2023). "Moreover, MTHFD2 was discovered to be positively associated with several immune checkpoints, such as cytotoxic T lymphocyte-associated antigen-4 (CTLA-4), PD-L1, T-cell immunoglobulin and mucin domain-3 (TIM-3), and Programmed Cell Death 1 (PD-1) in most cancers, especially in BLCA." (PMID 38130721, 2023).
cancer (continued). "In this study, we evaluated whether immune cells (CD4+ and CD8+ T cells) and immunosuppressive markers (PD-L1, CTLA-4, and IL-10) were present in peripheral blood and cancer tissues from GC patients, then investigated whether those findings were correlated with each other." (PMID 37153541, 2023). "Although BsAbs targeting CTLA-4 have been a significant breakthrough in the field of cancer immunotherapy, there are still numerous aspects that require clarification and challenges that need to be addressed related to the safety, effectiveness, and range of tumors that could be treated." (PMID 37441075, 2023). "In addition, CTLA-4 gene expression level tended to be higher in CTCs and PBMCs in patients with KRAS mutation than in patients with KRAS wild type (data obtained from Gold Coast University Hospital and detected by next-generation sequencing on cancer tissue)." (PMID 36902476, 2023). "Patients should not use anti-CTLA-4 antibodies when their microbiota have a low level of Bacteroidetes, and those with poor prognosis on genetic predisposition should attempt other types of cancer therapy instead." (PMID 38067327, 2023). "ICIs, including programmed death protein receptor-1 (PD-1), programmed death ligand-1 (PD-L1), and CTLA-4 inhibitors, are monoclonal antibodies used for the treatment of various malignancies across different clinical settings and have significantly improved the cancer-related outcomes." (PMID 37174104, 2023). "Therefore anti-CTLA-4 antibody is used for cancer immunotherapy." (PMID 36793737, 2023). "The assay could be applied in supporting the studies of CTLA-4-based cancer therapies." (PMID 37110545, 2023). "Furthermore, the effectiveness of ICITs such as anti-CTLA-4 and anti-PD-1/PD-L1 could represent a major improvement in life expectancy for patients with a variety of advanced cancer types." (PMID 37736849, 2023). "Therefore, CTLA-4 has been a hot target for mAbs cancer immunotherapy such as Ipilimumab." (PMID 36072957, 2022). "Moreover, blocking CTLA-4 enhances the antigen-presenting process, or the subsequent immune system attack is enhanced by blocking PD-1/PD-L1, finally establishing a stronger adaptive immune system to kill cancer cells." (PMID 35399527, 2022). "However, the majority of patients with cancer do not respond to dual PD-1 and CTLA-4 blockade, a treatment that often causes serious adverse events." (PMID 35316223, 2022). "T cells have been considered, for a long time, key players in anti-cancer responses triggered by treatment with immune checkpoint inhibitors, but our recent studies also revealed the critical role of NK cells, due to the expression of ICs, such as PD-L1 and CTLA-4, on these immune cells also." (PMID 36358708, 2022). "As a result, CTLA-4, PD-1, or PD-L1 inhibitors may be effective in cancer immunotherapies." (PMID 36119533, 2022). "One of the upmost achievements in cancer immunotherapies in the last decade has undoubtedly been the introduction of T cell-targeted immunomodulators, the immune checkpoint inhibitors (ICIs), such as antibodies against CTLA-4 and PD-1 or programmed death ligand-1 (PD-L1)." (PMID 36497465, 2022). "Notably, SLC2A1 was remarkably positively correlated with PD-L1 and CTLA4 in most cancers." (PMID 36358765, 2022). "Blockades of CTLA-4 and PD-1 function at different times in the immune cascade and at different locations, leading to the hypothesis that these therapies may have an additive or synergistic effect in the treatment of cancer." (PMID 36389815, 2022). "Furthermore, there was no significant inflammation observed; mice saw increased lifespans, with 40% survival after 40 days following aPD1-GOx-MN treatment and about 70% of T-cell promoting anti-CTLA4 antibody and aPDI treated mice being cancer-free beyond 60 days when the MN patch was used." (PMID 35049657, 2022). "In addition, EZH2 inhibition potentiates cancer response to anti-CTLA-4 and anti-PD1 therapies." (PMID 35008422, 2022).